CD80 (CD80 molecule)
Diseases named in the same sentence as CD80 in open-access papers (continued):
Sharing a sentence is not in itself a finding about the gene and the disease.
infection (continued). "Interestingly, P.gingivalis significantly reduced constitutive CD86, and CD80 levels in oDCs (51.06%, 47.8%) compared to control oDCs with no infection (27.6% and 33.9%) respectively." (PMID 34141629, 2021). "Furthermore, macrophages increased the expression of activation markers (CD80, CD86 and CD40) that was more evident at week 10 after infection while DCs of Treg depleted mice increased the expression of CD86 and CD40 at week 6 and CD80 and CD40 at week 10 after infection." (PMID 30410119, 2018). "The expression of CD80 on mDCs was not altered due to infection in either the neonates or adults." (PMID 28060871, 2017). "Infection with Y strain did not have a significant effect on the expression of CD80 or CD86." (PMID 26147698, 2015). "As expected, the level of CD80 RNA in HSV-CD80-infected DCs was significantly higher than in parental-infected DCs at 2, 4 and 8 hr PI (p<0.001), indicating that the presence of two copies of CD80 in HSV-CD80 leads to increased expression of CD80 during the early period of infection." (PMID 24475315, 2014). "Alternatively, Tregs may require CD86 in the context of a classic APC, and we have observed that MHC II+ mononuclear cells in the respiratory tract late after infection may express either CD80 or CD86 or both (data not shown)." (PMID 25144228, 2014). "mRNA expression measured at various time points (1, 3, 12, 24, 36 and 48 hpi) by real-time RT-PCR showed that infection of PK-15 cells with CSFV at either a MOI of 0.1 or 1.0, resulted in down-regulation of seven immune response genes, namely SLA-2, TAP1, SLA-DR, Ii, CD40, CD80, CD86." (PMID 22925563, 2012). "Costimulatory molecules (CD80, CD86, CD40, GITR, and ICOS), adhesion molecules (VCAM-1 and P-selectin), and signaling molecules involved in cytokine regulation (Tbx21 and Socs1) were also increased with Hb infection and decreased with anti-IL-7Rα M595 treatment in a dose-dependent manner." (PMID 23057802, 2012). "Monocyte HLA-DR and co-stimulatory molecules (CD80 and CD86), and an increase in soluble PD-L1, discriminate between critically ill patients, patients with mild infection, and patients with non-infectious illness." (PMID 41624862, 2026). "Upon infection with rRSV-A-0594-eGFP, the expression of CD86, but not that of CD80, was upregulated in eGFP+ PMs." (PMID 41280933, 2025). "Znfx1–/– BMDMs expressed significantly reduced levels of CD80, CD86, and MHC-II in response to H37Rv infection, without influencing the expression of CD206, a marker of type II macrophages." (PMID 38016036, 2024). "In summary, infection of microglia with MP-12 and ZH501 yielded different outcomes, with downregulation of CD45 and CD1b and no induction of CD86 and CD80 expression in response to ZH501 infection." (PMID 38392897, 2024). "We observed no reduction in MHC-II, CD80/86 and CD40 expression after infection, and similar levels of IFNγ production by Th1 cells were observed in time course studies." (PMID 38114497, 2023). "Infection with MERS-CoV also resulted in activation of the neutrophils, which were CD54+ and CD80+, whereas there was no change in the activation markers following infection with SAR-CoV-2, apart from the HLA-DR marker." (PMID 35891560, 2022). "The expression of activation markers CD80, CD86 and HLA-DR was strongly increased on macrophages following infection compared to the non-infected control." (PMID 35615366, 2022). "In contrast, infection with Ad5[P] or Ad5[PVP2]OP at MOI 250 led to a twofold increase of the MHC-II, CD80, and CD86 expression levels as compared to non-infected BMDCs." (PMID 33250878, 2020). "Induced expression of CD80 and CD86 was shown to enhance infection of species B Ads, but not HAdV-C5." (PMID 32957644, 2020). "CSFV is highly efficient in infecting and replicating in either moDC or bone marrow-derived DC (BMDC), although this infection did not result in any morphological, phenotypical (MHC I, MHC II, CD80/86 expression), or functional modulation of these cells." (PMID 31100880, 2019).
infection (continued). "At later time-points (week 4 post-infection), MHCII expression was lower in the absence of IL-4Rα on DCs whilst CD80 expression was similar between CD11ccreIL-4Rα−/lox and littermate control mice." (PMID 32039054, 2019). "Whereas previous reports, analyzing late points after infection, were not able to show activation by DCs upon CVB3, our findings show that WT DCs up-regulate CD80 and CD86 as early as 6 hours after CVB3 infection." (PMID 28973047, 2017). "We also assessed the expression of CD80 by CD11c+ DC and CD14+ monocytes but did not observe any significant changes after FMDV A24 Cruzeiro infection." (PMID 27008425, 2016). "Although MΦ up-regulated MHCI and CD80 and showed temporary upregulation of MHCII after infection with R. typhi in vitro, neither proinflammatory cytokines including IL-12 nor bactericidal NO were released." (PMID 27875529, 2016). "Mice that were genetically engineered to lack two co-stimulatory molecules called CD80 and CD86 failed to accumulate active CD8+ T cells in response to infection with a herpes-like virus." (PMID 26263500, 2015). "Surface expressions of MHCII, CD80 and CD86 were increased after infection, indicating maturation of cells, but were not appreciably different between the genotypes." (PMID 24728387, 2014). "A knockout mouse lacking both B7-family receptors CD80 and CD86 has severe defects in IFNγ secretion by T cells and the response to secondary infection, in addition to a failure to produce neutralizing antibodies and maintain long-term control of latency." (PMID 24587276, 2014). "Cells were monitored during infection and analyzed to ensure the absence of macrophage or dendritic cell markers (CD11c+, CD11b+, CD141+, CD303+, CD11b+, CD68+, CD80+)." (PMID 23717203, 2013). "Here, the expression of CD68, CD80, CD86, HLA-DR, MMR, TLR2 and TLR4 was analyzed under different experimental conditions (plus or minus exposure to CS, and with or without Mtb-infection)." (PMID 24278357, 2013). "When correlating our cytokine data to upregulation of CD80 and PDL1 we found that upregulation of CD80 and PDL1 is not always accompanied by production of pro-inflammatory cytokines upon EV1 infection." (PMID 23638101, 2013). "In contrast, TNFα, CD80 and A3Z1 and IL-10 expression did not increase upon infection with most of the strains." (PMID 24070317, 2013). "Flow cytometry analysis of infected cells did not reveal a statistically significant increase in CD40, CD80 and CD86 surface expression in DCs infected with btpB mutant when compared to the wild type at 8 h post-infection." (PMID 23847770, 2013). "cLN analyzed at 12 hours post-infection demonstrated no increase in CD69, CD80, or CD86 under any conditions (data not shown)." (PMID 22393351, 2012). "The inducible expression of positive and negative costimulatory molecules (CD80, CD86, B7-H1) by microglia was also examined following infection to gain further insight into their function during acute TMEV infection in vivo." (PMID 21494618, 2011). "Flow cytometry analysis of cell surface expression markers CD40, CD54, CD80, CD83, CD86 and HLA DR in infected DC revealed significant (p < 0.05) up regulation following infection with M. tuberculosis in comparison to immature DC with no stimulation." (PMID 21777464, 2011). "While CD68 expression did not change with infection or treatment, Mtb infection resulted in the elevated expression of HLA-DR and CD200R, while activation markers such as CCR7, CD80/CD86, and CD64 as well as scavenger receptors CD163 and CD206 were reduced on Mtb-infected cells." (PMID 40305296, 2025). "Interestingly, MP-12 infection elicited robust expression of both CD86 and CD80, whereas ZH501 infection did not lead to significant upregulation of either protein." (PMID 38392897, 2024).
infection (continued). "In contrast to our study, infection with a low-dose of non-neurotrophic H1N1 strain of influenza A virus (IAV) induced the activation of microglia, which expressed MHC-I and MHC-II, and other markers of activation such as CD80 and F4/80." (PMID 39770367, 2024). "For all classes of potential APCs at the infection site (i.e., monocytes, macrophages, and DCs), expression of CD40 and CD80 on both T. cruzi-infected and noninfected cells was at the level of naive cells through 4 days postinfection and became significantly different by day 6 postinfection." (PMID 36695605, 2023). "It should be noted that during the course of the respective antigen presentation experiments (48 hpi), siRNA-mediated silencing of Beclin-1 and Atg7 did not affect expression and/or infection-dependent induction of surface MHC I (H-2Kb and H-2Db), CD80, CD86, PD-L1 or PD-L2." (PMID 28634388, 2017). "Finally, we were able to reduce immunodominance after i.d., but not i.p. infection, using a VACV expressing the costimulators CD80 (B7-1) and CD86 (B7-2), which is notable because VACV-based vaccines incorporating these molecules are in clinical trials." (PMID 23633956, 2013). "This hypothesis was tested in this study and found that always females have higher expression of MHC-II, CD80, CD86, PD-L1, and PD-L2 during infection, but not in response to saline or TcEx." (PMID 23533995, 2013). "Moreover, while the primary T-cell response to infection is CD80/CD86-dependent on secondary infection, memory helper T cells do not require CD80 or CD86 costimulation for their activation to protect against challenge." (PMID 23053394, 2012). "In addition, in the absence of CD40, CD40L or CD80/CD86, viral reactivation in the lungs was observed at later time points after infection." (PMID 19621080, 2009). "Therefore, the increase in CD80 expression in B cells in HAM/TSP patients, which occurs despite a decrease in total B cell levels, likely reflects disease progression rather than prolonged infection or disease duration." (PMID 24472094, 2014). "Significant (p < 0.05) up regulation in cell surface expression of CD40, CD80, CD54 and MHC class II and CD86 and CD83 were observed both in LPS stimulated and H37Rv infected in comparison to negative control DC with media alone without any stimulation/infection." (PMID 21777464, 2011).
immune dysfunction (9 papers, 2015 to 2024). "CTLA-4 interacts with CD80, thereby limiting T-cell activation and leading to immune dysfunction." (PMID 38983866, 2024). "It has been proposed that CD80 plays a vital role in the “two-hit” podocyte immune disorder of MCD." (PMID 33194357, 2020). "Impaired recognition of pathogen-associated molecular patterns (PAMPs) to active innate immune responses, reduced expression of co-stimulatory molecules (CD80, CD86) and reduced antigen presenting capability, have also been reported to contribute to uremic immune dysfunction." (PMID 30619252, 2018). "Considering that T cell-stimulating factor such as CD80, CD86, and OX40L are positively regulated by PU.1 in DCs, PU.1 knockdown may be a favorable strategy in some immune disorders." (PMID 27708417, 2016).
adenocarcinoma (6 papers, 2015 to 2025). A common cancer characterized by the presence of malignant glandular cells. "Subgroup analysis restricted to patients with adenocarcinoma or those that did not have a complete response to CRT yielded similar results with the notable exception being enrichment of HLA-DR/CD80+/CD86+ expression in patients without a history of relapse." (PMID 39751903, 2025).
bacterial infection (6 papers, 2013 to 2022). "Mean fluorescence values of MHC II, CD40, and CD80 in O. tsutsugamushi-infected DCs increased by more than 2 fold when compared to those of un-stimulated immature DCs, indicating that bacterial infection induced DC activation." (PMID 23301113, 2013).
cardiovascular disease (5 papers, 2016 to 2023). "In the present study, we found that prebiotic/probiotic supplementation reduced ARG1 (30 days), ATM (90 days), and CD80 (60 days), which may translate to a reduced cardiovascular disease risk." (PMID 36437471, 2022). "Moreover, the exact number of CD80+ cells in kidneys of individuals without cardiovascular disease was slightly higher than in fatal MI, and the number of CD206+ cells was strikingly predominant." (PMID 37509483, 2023). "After careful investigation of the 14 cardiovascular disease-related genes via literature review, we found 13 of them have literature support that are associated with CHD (VSD is the most common type of CHD), while CD80 has no explicit support." (PMID 31440271, 2019).
hematological malignancies (5 papers, 2013 to 2023). "The ligands for PD-1, programmed cell death ligand 1 (PD-L1) and programmed cell death ligand 2‚ as well as the ligands for CTLA-4, B7-1 (CD80), and B7-2 (CD86), are upregulated in both solid tumors and hematological malignancies." (PMID 33931473, 2021).
infectious disease (4 papers, 2014 to 2024). A disorder directly resulting from the presence and activity of a microbial, viral, or parasitic agent in humans. "Further review of the ‘immune response’ GO cluster and genes within this category (CD1A, CD80, CD86, and HLA-DQB1) revealed related pathways which were in the same biological process associated with numerous autoimmune and infectious diseases." (PMID 38448477, 2024). "Taken together, in both autoimmune and infectious diseases a substantial amount of data is available on the differential regulation of CD80 vs. CD86, supporting our hypothesis of deleterious and protective roles for CD80+ and CD86+ B cells, respectively, in HAM/TSP pathogenesis." (PMID 24472094, 2014).
blood cancers (3 papers, 2020 to 2024). "In addition to solid cancers, we also identified a number of hematological malignancies that co-express high levels of CD80 and PTK2, highlighting potential opportunities for the development of FAK inhibitors for the treatment of some blood cancers." (PMID 31959281, 2020).
colon (3 papers, 2015 to 2019). "Our first step in investigating the role of DNA methylation in CRC immune surveillance consisted in examining the expression of CD80; we then went on to analyze its relationship with genomic methylation during the early stages of colon carcinogenesis." (PMID 27377375, 2016).
CD80 also shares sentences with these, for which no sentence is quoted: focal segmental glomerulosclerosis (8 papers); multiple myeloma (6); glomerulopathies (5); head and neck squamous cell carcinoma (5); sarcoidosis (4); colorectal (3); hematologic cancers (3); Insulin resistance (3); ulcerative colitis (3); autoimmune thyroiditis (2); Chlamydia infection (2); Cognitive impairment (2); coronary artery disease (2); food allergy (2); glomerulosclerosis (2); malignant glioma (2); membranous nephropathy (2); metastatic carcinoma (2); neurodegenerative disease (2); osteoporosis (2); plaque psoriasis (2); psoriatic arthritis (2); rheumatic disease (2); serous ovarian cancer (2); sialadenitis (2); Adult onset (1); adult T cell leukemia (1); airway allergy (1); airway hyperresponsiveness (1); anthrax infection (1).
A further 93 diseases each share a sentence with CD80 in 1 paper.